PCMT1 (protein-L-isoaspartate (D-aspartate) O-methyltransferase)
Description:
Initiates the repair of damaged proteins by catalyzing methyl esterification of L-isoaspartyl and D-aspartyl residues produced by spontaneous isomerization and racemization of L-aspartyl and L-asparaginyl residues in aging peptides and proteins. Acts on EIF4EBP2, microtubule-associated protein 2, calreticulin, clathrin light chains a and b, Ubiquitin C-terminal hydrolase isozyme L1, phosphatidylethanolamine-binding protein 1, stathmin, beta-synuclein and alpha-synuclein (By similarity).
Synonyms: PIMT
Tractability: Small molecule: a structure with a bound ligand is known; it has a high-quality binding pocket. PROTAC: ubiquitination databases record sites on it; its protein half-life has been measured.
Target class: Enzyme; Transferase
Gene: Protein-coding gene on chromosome 6 (149,749,431 to 149,811,421, forward strand). Ensembl gene ENSG00000120265.
Subcellular location: Cytoplasm, cytosol
Subcellular location (Human Protein Atlas): Cytosol
Pathways (Reactome):
Metabolism of proteins: Protein repair
Gene Ontology:
Molecular function: cadherin binding; protein binding; protein-L-isoaspartate (D-aspartate) O-methyltransferase activity
Biological process: protein repair
Cellular component: cytosol; extracellular exosome; extracellular vesicle
Genetic constraint (gnomAD): Loss-of-function variants: 3 observed, 10.81 expected, observed/expected ratio (o/e) 0.28, 90% interval 0.12 to 0.72. The upper end of that interval is the gene's LOEUF score, 0.72, which puts it in group 2 of 6, group 1 being the genes least tolerant of losing a copy. Missense variants: 86 observed, 116.64 expected, observed/expected ratio (o/e) 0.74, 90% interval 0.62 to 0.88. Synonymous variants: 46 observed, 44.22 expected, observed/expected ratio (o/e) 1.04, 90% interval 0.82 to 1.33.
Homologues: Orthologues: chimpanzee PCMT1 (99% identical), macaque PCMT1 (99% identical), pig PCMT1 (98% identical), rabbit PCMT1 (98% identical), guinea pig PCMT1 (97% identical), dog PCMT1 (97% identical), mouse Pcmt1 (95% identical), rat Pcmt1 (95% identical), tropical clawed frog pcmt1 (91% identical), zebrafish pcmt (84% identical), Drosophila melanogaster Pcmt (55% identical), Caenorhabditis elegans pcm-1 (52% identical). Paralogues in human: PCMTD1 (25% identical), PCMTD2 (24% identical).
Diseases named in the same sentence as PCMT1 in open-access papers:
PCMT1 is named in the same sentence as 49 diseases in open-access papers, as found by Europe PMC text mining. Sharing a sentence is not in itself a finding about the gene and the disease. The quoted sentences say what the papers report.
breast carcinoma (11 papers, 2021 to 2026). "In this study, we silenced PCMT1 in MDA-MB-231 cells and explored its downstream molecular targets to decipher the underlying mechanisms by which PCMT1 promotes the progression of breast cancer." (PMID 37953789, 2023). "The expression level, mutation, immune correlation, and coexpression of PCMT1 in breast cancer were studied using the following databases: UALCAN database, Human Protein Atlas database, cBioPortal database, TIMER database, and LinkedOmics database." (PMID 35535040, 2022). "The results showed that PCMT1 has the highest mutation frequency in soft tissue sarcoma, esophagogastric cancer, and breast cancer." (PMID 35535040, 2022). "Then, we studied the PCMT1 gene mutation in breast cancer patients of TCGA Firehose Legacy (n = 1108 patients)." (PMID 35535040, 2022). "PCMT1 overexpression was also associated with shorter survival in breast cancer." (PMID 39235556, 2025). "The studies conducted so far show that PCMT1 expression is correlated with the advanced tumor stage of breast cancer and that the association with immune-infiltration biomarkers suggest that it may be a prognostic marker of breast cancer." (PMID 39235556, 2025). "Studies show an association of elevated PCMT1 levels with various cancer types like breast cancer." (PMID 37759792, 2023). "As an oncogene, protein-L-isoaspartate (D-aspartate) O-methyltransferase (PCMT1) is a prognostic biomarker in breast cancer and is highly expressed, while its underlying functions remain unknown." (PMID 37953789, 2023). "TIP analysis showed that PCMT1 was significantly associated with breast cancer priming and activation (step 3), trafficking of immune cells to tumors (step 4), infiltration of immune cells into tumors (step 5), and recognition of cancer cells by T cells (step 6)." (PMID 35535040, 2022). "In addition, we assessed the association between the expression of PCMT1 in breast cancer and tumor staging." (PMID 35535040, 2022). "The KM survival curve was drawn based on the TCGA data set and showed that high PCMT1 expression may be a risk factor for poor prognosis in breast cancer patients (HR: 1.92 (1.38, 2.67), P = 0.0001)." (PMID 35535040, 2022). "To compare our results with other types of breast cancer, we used the Human Protein Atlas database and evaluated the overexpression of PCMT1 in clinical breast-cancer samples." (PMID 39235556, 2025). "The current study investigates the potential role of BAP31 in regulating breast cancer progression through its interaction with PCMT1." (PMID 40332113, 2025). "We observed strong PCMT1 immunoreactivity in breast-cancer samples, which was significantly higher than in the control group (median H-SCORE = 148 vs. 128.5, respectively, p = 0.036)." (PMID 39235556, 2025). "We observed strong PCMT1 immunoreactivity in breast cancer samples and PCMT1 expression in TNBC was significantly higher than in the control group." (PMID 39235556, 2025). "To determine the prognostic value of PCMT1 expression in patients with breast cancer, we divided the samples into low and high PCMT1 expression groups, with the cutoff point as 27.25." (PMID 39235556, 2025). "In luminal A and luminal B breast cancers, PCMT1 levels were higher in samples from patients older than 55 years of age compared to younger patients." (PMID 39235556, 2025). "Additional studies show that the inhibition of PCMT1 induced apoptosis and suppressed cell proliferation and invasion in breast-cancer cells." (PMID 39235556, 2025). "PCMT1 expression in breast cancer samples was significantly higher in the cancer group than in the control group (median H-SCORE = 4.824 vs. 4.618, respectively, p = 0.0004)." (PMID 39235556, 2025). "PCMT1 expression was prognostic of OS in the TCGA cohort, and its high expression correlated with shorter OS in breast cancer." (PMID 39235556, 2025).
breast carcinoma (continued). "PCMT1 is overexpressed in TNBC which is associated with significantly shorter overall survival of patients in both the study group and TCGA Breast Cancer Cohort." (PMID 39235556, 2025). "To find out the characteristics of PCMT1 staining patterns in breast cancer and the control group, we performed immunohistochemical staining using anti-PCMT1 monoclonal antibodies." (PMID 39235556, 2025). "The role of PCMT1 as a predictive marker was suggested not only in breast cancer but also in other malignancies." (PMID 39235556, 2025). "A previous study has demonstrated the prognostic value of PCMT1 in breast cancer (Guo, Du & Li, 2022a)." (PMID 37953789, 2023). "Emerging research indicates that PCMT1 expression influences immune infiltration in breast cancer, and related studies have corroborated PCMT1 as a crucial driver of ovarian cancer metastasis." (PMID 37596654, 2023). "A recent study demonstrated that the level of PCMT1 in breast cancer cells is significantly high (Guo, Du & Li, 2022a)." (PMID 37953789, 2023). "A recent study demonstrated the cellular functions and upstream regulatory axis of PCMT1 in breast cancer cell lines." (PMID 37953789, 2023). "Some proteins are considered to be involved in the regulation of breast cancer, including PCMT1 that is related to the abundance of immune infiltration." (PMID 37953789, 2023). "In summary, we identified the cellular functions and molecular targets of PCMT1 in TNBC MDA-MB-231 cells, expanding our understanding of the functions of PCMT1 in breast cancer." (PMID 37953789, 2023). "The expression of PCMT1 in breast cancer tissues was significantly higher than that in normal tissues (P = 2.2E − 49), and this differential expression was also verified in GSE3744 (P = 5.7E − 5)." (PMID 35535040, 2022). "Based on the online server Kaplan–Meier plotter, we evaluated the relationship between the expression level of PCMT1 and the survival of breast cancer patients to reveal the prognostic value of PCMT1 in breast cancer." (PMID 35535040, 2022). "Based on the raw count of the RNA sequencing data of 1097 breast cancer tumors downloaded from the TCGA data set and the corresponding clinical information, we studied the prognostic effect of the PCMT1 gene on breast cancer." (PMID 35535040, 2022). "Previous studies and databases have reported that PCMT1 expression is positively correlated with poor prognosis in several human cancers, including breast cancer, bladder cancer, and endometrial cancer." (PMID 35033172, 2022). "The potential biological mechanism of PCMT1 in breast cancer, its potential relationship with tumor immune escape, and its clinical role still need to be further studied." (PMID 35535040, 2022). "Based on the CCLE database, we explored the expression level of PCMT1 in different breast cancer cell lines, and the expression level of PCMT1 was significantly different in different breast cancer cell lines." (PMID 35535040, 2022). "Survival analysis revealed that high PCMT1 expression is significantly associated with shorter overall survival (OS), relapse-free survival (RFS), and postprogression survival (PPS) in breast cancer patients." (PMID 35535040, 2022). "To account for this difference, we analyzed the correlation of PCMT1 methylation and mRNA expression in breast cancer using the gene set cancer analysis (GSCA) database, which showed a significant negative correlation." (PMID 35535040, 2022). "The analysis of breast cancer immune infiltration indicated that PCMT1 was significantly related to biomarkers of breast cancer immune infiltrating cells." (PMID 35535040, 2022). "PCMT1 can be used as a potential prognostic biomarker of breast cancer, and it is significantly related to the abundance of breast cancer immune infiltration." (PMID 35535040, 2022). "We used bc-GenExMiner v4.7 to explore the relationship between PCMT1 and clinical pathological parameters of breast cancer." (PMID 35535040, 2022).
breast carcinoma (continued). "Our research results will provide certain reference value for further research on the role of PCMT1 in breast cancer." (PMID 35535040, 2022). "Based on the TCGA-BRCA data set, we obtained the differential expression of PCMT1 in breast cancer tissues and normal tissues." (PMID 35535040, 2022). "ROC curves and nomograms verify the effectiveness of PCMT1 as a prognostic biomarker for breast cancer." (PMID 35535040, 2022). "PCMT1 is significantly high in breast cancer, and it is significantly related to the abundance of immune infiltration." (PMID 35535040, 2022). "Using the Human Protein Atlas database, we assessed the expression level of PCMT1 through immunohistochemical images of PCMT1 in clinical breast cancer samples." (PMID 35535040, 2022). "The protein expression level of PCMT1 in breast cancer tissues (n = 125) was lower than that in normal tissues (n = 18)." (PMID 35535040, 2022). "Studies have shown that breast cancer patients with higher PCMT1 expression have significantly lower survival rates than those with lower PCMT1 expression." (PMID 33898446, 2021). "The result indicated that the DSVs in SNTG2, PCMT1, DACT2, CBX3, ATP11A, and SHC2 were associated with breast cancer." (PMID 33431054, 2021). "Increased PCMT1 expression is associated with a bad prognosis in breast cancer patients; however, its prognostic value in TNBC is not fully known." (PMID 39235556, 2025). "Furthermore, we provide the novel evidence that BAP31 interacts with PCMT1, initiating a cascade of effects on breast cancer cells." (PMID 40332113, 2025). "Moreover, multivariate Cox regression analysis indicated that age, high PCMT1 expression, and recurrence were statistically significant prognostic factors of overall survival in the TCGA breast-cancer cohort." (PMID 39235556, 2025). "The results showed a similar correlation—PCMT1 was overexpressed in breast cancer cells." (PMID 39235556, 2025). "In this study, we focused on the assumption that PCMT1 may regulate breast cancer-related processes by influencing the global transcriptome profile, including gene expression and alternative splicing events (ASEs)." (PMID 37953789, 2023). "Through pancancer and related bioinformatics analysis of PCMT1 in breast cancer, it will help us understand the related functions of PCMT1 in breast cancer and provide new insights for breast cancer drug development and clinical exploration of molecular markers for diagnosis and prognosis." (PMID 35535040, 2022). "This suggests that PCMT1 may have the function of a biomarker for the early diagnosis of breast cancer." (PMID 35535040, 2022). "Then, we specifically studied the expression of PCMT1 in breast cancer." (PMID 35535040, 2022). "In summary, our results show that the high expression of PCMT1 is significantly related to the poor prognosis of breast cancer, may be a potential biomarker of breast cancer, and is significantly related to the immune infiltration of breast cancer." (PMID 35535040, 2022). "While the molecular targets of PCMT1 in breast cancer remain unknown." (PMID 37953789, 2023). "We observed that the PCMT1 gene was significantly up-regulated in 10 tumors including colon adenocarcinoma (COAD, tumor: 5.57 ± 0.42; normal: 5.44 ± 0.19, P = 8.4e − 4) and breast carcinoma (BRCA, tumor: 6.04 ± 0.60; normal: 5.79 ± 0.20, P = 9.8e − 11)." (PMID 35535040, 2022). "Therefore, we speculate that the inconsistency of PCMT1 mRNA and protein expression in breast cancer stems from the inhibition of posttranslational modification and other processes in breast cancer, resulting in lower protein expression levels than normal tissues." (PMID 35535040, 2022). "However, the prognostic value of PCMT1 in breast cancer remains unclear." (PMID 35535040, 2022).
breast carcinoma (continued). "The survival analysis of PCMT1 in breast cancer showed that the high expression of PCMT1 can lead to shorter OS, RFS, and PPS in breast cancer patients, suggesting that high expression of PCMT1 is significantly related to the poor prognosis of breast cancer." (PMID 35535040, 2022). "In accordance with the gene expression levels, the protein levels of ZDHHC9, PCMT1, TMEM70 were significantly higher in breast cancer, and the protein levels of IRF2, KCNJ11 were higher in normal tissues." (PMID 34956313, 2021). "Although it has been confirmed that PCMT1 is involved in the occurrence and development of several cancers and its prognostic role has been emphasized, the role of PCMT1 in breast cancer has not been confirmed." (PMID 35535040, 2022). "The results showed that the PCMT1 gene is a variable independent of other clinical factors and can guide the prognosis of breast cancer." (PMID 35535040, 2022).
bladder cancer (8 papers, 2019 to 2025). "High expression of PCMT1 was present in bladder cancer cells and associated with a poorer prognosis for patients." (PMID 39235556, 2025). "In contrast to our study, PCMT1 protein overexpression is positively correlated with metastasis among ovarian and bladder cancer patients, indicating the biologic function of PCMT1 in regulating cell proliferation, migration and invasion in cancer cell lines." (PMID 39235556, 2025). "PCMT1 expression is closely related to clinical grade, muscle infiltration, lymph node metastasis and distant metastasis of bladder cancer patients." (PMID 37899170, 2023). "Recent evidence documents that PCMT1 is an unfavorable prognostic predictor and functions as an oncogene in various cancers, including bladder cancer and lung adenocarcinoma, indicating a role for PCMT1 in cancer progression." (PMID 35033172, 2022). "PCMT1 expression was high in bladder cancer tissues, and the expression level of PCMT1 was related to the metastasis, staging, and grading of bladder cancer." (PMID 33898446, 2021). "Here, our results demonstrated that PCMT1 inhibited bladder cancer cell apoptosis, and silencing PCMT reduced the inhibitory effect of LINC00511 on apoptosis." (PMID 33898446, 2021). "Our previous studies have shown that PCMT1 is an adverse prognostic biomarker involved in bladder cancer cell migration and invasion by regulating EMT-related genes." (PMID 33898446, 2021). "As the expression of DPP7/2 is downregulated in CRC tumor tissues, it shows inverse correlation with PCMT1, which has been shown to express at higher amounts in bladder cancer." (PMID 31387239, 2019). "PCMT1 has also confirmed to be an unfavorable prognostic factor in bladder cancer." (PMID 37899170, 2023). "Previous studies have shown that strong PCMT1 expression is not only a predictive marker for poor prognosis of surgically removed lung adenocarcinoma but also an unfavorable prognostic biomarker for bladder cancer." (PMID 35535040, 2022). "The results showed that LINC00511 could target miR-143-3p/PCMT1 to regulate the proliferation, migration, and apoptosis of bladder cancer TCCSUP or SW780 cells and promote the occurrence and development of bladder cancer." (PMID 33898446, 2021). "In addition, a study of PCMT1 in bladder cancer showed that PCMT1 regulates the migration and invasion of bladder cancer cells, promotes the occurrence and development of bladder cancer, and emphasizes that PCMT1 is an unfavorable prognostic biomarker for bladder cancer." (PMID 35535040, 2022). "The expression level of PCMT1 in bladder cancer cells and tissues is increased significantly compared to normal uroepithelial cells and tissues." (PMID 37899170, 2023).
epilepsy (3 papers, 2012 to 2020). A brain disorder characterized by episodes of abnormally increased neuronal discharge resulting in transient episodes of sensory or motor neurological dysfunction, or psychic dysfunction. "Examples include a mouse model for Down’s syndrome (Ts65DN), heregulin (a ligand for tyrosine receptor kinase) mutant mice, an epilepsy model deficient in a repair protein L-isoaspartate (d-aspartate)-O-methyltransferase (Pcmt1−/−) and Huntington triplet deletion mice Hdh (∆Q/∆Q) mice." (PMID 22647713, 2012). "Down-regulation of PCMT1 in human epileptic hippocampus suggests there may be a conserved role of PCMT1 in seizure disorders." (PMID 23071621, 2012). "Similar to Pcmt1 knockout mice, however, knockout mice of the β1 isoform of PLC developed epilepsy, indicating that the epileptic seizures in the Pcmt1 knockout mice may be mechanistically connected to PLC function, although this remains highly speculative at this point." (PMID 33552132, 2020).
hepatocellular carcinoma (3 papers, 2017 to 2023). A malignant tumor that arises from hepatocytes. "The PCMT1 gene encodes a repair enzyme protein, which prevents Bax-induced apoptosis in neuronal cells and can be used as a potential therapeutic target for hepatocellular carcinoma." (PMID 29212247, 2017). "In this study, we discovered that PCMT1 was overexpressed in hepatocellular carcinoma." (PMID 37596654, 2023). "This proves that PCMT1 is involved in the regulation of hepatoma cell apoptosis." (PMID 35535040, 2022).